HOOK2 (hook microtubule tethering protein 2)
Description:
Component of the FTS/Hook/FHIP complex (FHF complex). The FHF complex may function to promote vesicle trafficking and/or fusion via the homotypic vesicular protein sorting complex (the HOPS complex). Contributes to the establishment and maintenance of centrosome function. May function in the positioning or formation of aggresomes, which are pericentriolar accumulations of misfolded proteins, proteasomes and chaperones. FHF complex promotes the distribution of AP-4 complex to the perinuclear area of the cell.
Synonyms: HK2
Tractability: PROTAC: ubiquitination databases record sites on it; its protein half-life has been measured.
Gene: Protein-coding gene on chromosome 19 (12,762,640 to 12,872,740, reverse strand). Ensembl gene ENSG00000095066.
Subcellular location: Cytoplasm, cytoskeleton, microtubule organizing center, centrosome; Cytoplasm; Cytoplasm, cytoskeleton; Golgi apparatus, trans-Golgi network
Subcellular location (Human Protein Atlas): Cytosol; Vesicles
Gene Ontology:
Molecular function: identical protein binding; protein binding; dynein light intermediate chain binding; microtubule binding
Biological process: early endosome to late endosome transport; endosome organization; endosome to lysosome transport; lysosome organization; protein localization to perinuclear region of cytoplasm; cytoplasmic microtubule organization; cytoskeleton-dependent intracellular transport; endocytosis; protein transport along microtubule
Cellular component: centrosome; cytoplasm; cytosol; FHF complex; HOPS complex; trans-Golgi network; cytoskeleton; Golgi apparatus
Genetic constraint (gnomAD): Loss-of-function variants: 109 observed, 110.22 expected, observed/expected ratio (o/e) 0.99, 90% interval 0.85 to 1.16. The upper end of that interval is the gene's LOEUF score, 1.16, which puts it in group 5 of 6, group 1 being the genes least tolerant of losing a copy. Missense variants: 978 observed, 944.22 expected, observed/expected ratio (o/e) 1.04, 90% interval 0.98 to 1.09. Synonymous variants: 405 observed, 385.7 expected, observed/expected ratio (o/e) 1.05, 90% interval 0.97 to 1.14.
Homologues: Orthologues: chimpanzee HOOK2 (99% identical), macaque HOOK2 (97% identical), dog HOOK2 (93% identical), pig HOOK2 (92% identical), guinea pig HOOK2 (88% identical), mouse Hook2 (82% identical), rat Hook2 (79% identical), tropical clawed frog hook2 (54% identical), zebrafish HOOK2 (34% identical), Drosophila melanogaster hook (30% identical), Drosophila melanogaster Girdin (19% identical), Caenorhabditis elegans zyg-12 (18% identical), and 2 more. Paralogues in human: HOOK3 (50% identical), HOOK1 (48% identical), CCDC88A (28% identical), CCDC88C (28% identical), CCDC88B (21% identical).
Diseases named in the same sentence as HOOK2 in open-access papers:
HOOK2 is named in the same sentence as 17 diseases in open-access papers, as found by Europe PMC text mining. Sharing a sentence is not in itself a finding about the gene and the disease. The quoted sentences say what the papers report.
Obesity (4 papers, 2017 to 2025). Accumulation of substantial excess body fat. "The Hook Microtubule Tethering Protein 2 (HOOK2) gene is another epigenetic contributor to increased rates in obesity within the Hispanic population." (PMID 37239728, 2023). "The differential methylation profile of the HOOK2 gene in individuals with T2D and obesity might be related to the attendant T2D, but further studies are required to identify the potential role of HOOK2 gene in T2D disease." (PMID 29228058, 2017). "The significant hypermethylation observed on the cg04657146-region in T2D female samples indicates it may be a key region of the HOOK2 gene for DNA modification potentially involved in attendant T2D in individuals with obesity, especially females." (PMID 29228058, 2017). "Individuals with obesity and type 2 diabetes have reported abnormal intragenic DNA methylation of HOOK2 when compared to individuals with non-diabetic conditions." (PMID 41373473, 2025). "DNA methylation of genes identified such as SLC2A9, HOOK2, LTF, and DUSP22 all have direct or indirect links to diabetes or obesity including immune or inflammatory regulatory pathways, signaling pathways, and clinical disorders related to diabetes and obesity." (PMID 32075680, 2020).
diabetes (3 papers, 2015 to 2023). "The effects of diabetes were partly mediated by the altered methylation of HOOK2, LCE3C, and TMEM63B." (PMID 32075680, 2020). "Others have been associated with diabetes (ZBED3), asthma (EMID2), and cancer (FBXO3, HOOK2, MT2A, EIF3E, RPH3AL, PTRF, MT1M, STK32A)." (PMID 25748564, 2015).
type 2 diabetes (3 papers, 2017 to 2025). "We found significant differential methylation between T2D and NT2D samples in 24 CpGs that map with sixteen genes, one of which, HOOK2, demonstrated a significant correlation between differentially hypermethylated regions on the gene body and the presence of type 2 diabetes." (PMID 29228058, 2017).
asthma (2 papers, 2015 to 2020). "For the remaining genes (airway fibroblasts: HOOK2 and HOXA7; parenchymal fibroblasts: HOXA5, HOXA6, HOXA-AS3, RB1 and NR2F1-AS1), there was no differential gene expression between donors with and without asthma." (PMID 33008450, 2020).
Alzheimer disease (1 paper, 2021). A progressive, neurodegenerative disease characterized by loss of function and death of nerve cells in several areas of the brain leading to loss of cognitive function such as memory and language. "Hook2 is implicated in the formation of aggresomes, vesicle trafficking, and fusion, particularly in degradation of neuronal tau aggregates in Alzheimer’s disease (AD)." (PMID 34680941, 2021).
amyloidoses (1 paper, 2015). "The homology of Btn2p to human HOOK proteins, a family that includes the aggresome-promoting protein HOOK2, suggests that information gleaned from the yeast systems will have application in efforts to control human prions and amyloidoses." (PMID 25654539, 2015).
bladder cancer (1 paper, 2025). "To investigate the protein expression profiles of six genes (ABCA7, HOOK2, JUNB, RHOB, VMP1, and ACTG1) that significantly impact both DSS and PFI in bladder cancer patients, we conducted Western blot analyses using SV-HUC-1 and 5637 cell lines." (PMID 40574864, 2025).
gestational diabetes (1 paper, 2020). Carbohydrate intolerance first diagnosed during pregnancy. "In an additional DNA methylation study on mothers with gestational diabetes, HOOK2 was found to be commonly differentially methylated in the maternal blood, placenta, and umbilical cord." (PMID 32075680, 2020).
laryngeal carcinoma (1 paper, 2021). Carcinoma that arises from the laryngeal epithelium. "Moreover, LAT2 (HR: 0.525901, 95% CI: 0.320208-0.863728, p-value = 0.011127) and HOOK2 (HR: 0.458976, 95% CI: 0.25448-0.827801, p-value = 0.009654) were protective factors for laryngeal cancer." (PMID 34976784, 2021). "Our data confirmed that RCN1, DNAJA2, LASP1 and IBSP were up-regulated while LAT2, FUZ, HOOK2 and DAPK2 were down-regulated in laryngeal cancer." (PMID 34976784, 2021).
ovarian carcinoma (1 paper, 2026). A malignant neoplasm originating from the surface ovarian epithelium. "Given the profound impact of reduced HOOK2 levels on ovarian cancer cells, this gene emerges as a promising therapeutic strategy for treating ovarian cancer patients." (PMID 42031698, 2026). "The findings reveal that a decrease in HOOK2 levels leads to diminished growth and cellular migration in ovarian cancer cells, impeding the in vivo formation of tumors." (PMID 42031698, 2026). "There is evidence suggesting that HOOK2, an adaptor protein involved in microtubule transport, may play a role in cancer, particularly ovarian cancer." (PMID 42031698, 2026). "Moreover, the study observes that the decrease in HOOK2 diminishes the properties of cancer stem cells in ovarian cancer, possibly due to the increase in cell death specifically found within these stem cells." (PMID 42031698, 2026).
ovarian tumors (1 paper, 2026). "This study examines the role of HOOK2 in the progression of ovarian tumors." (PMID 42031698, 2026).
prediabetes (1 paper, 2025). "A total of 130 DMCs across 99 genes, including LCLAT1, HLA-C, ZNF714, and HOOK2, were shared by prediabetes and T2D groups." (PMID 41373473, 2025). "Compared to the control group, we detected 130 DMCs that were shared between the prediabetes and T2D groups, with LCLAT1, HLA-C, NINJ2, ZNF714, CNDP2, and HOOK2 among the top differentially methylated genes." (PMID 41373473, 2025).
cancer (4 papers, 2015 to 2026). A tumor composed of atypical neoplastic, often pleomorphic cells that invade other tissues. "Moreover, SEMA4B and HOOK2 were significantly associated with MSI in more than 10 cancers." (PMID 40574864, 2025). "In four female carcinoma samples (COAD, HNSC, LUSC, and PAAD), three genes (AFAP1, NINJ2, and HOOK2) were commonly identified as classifiers, and the overexpression of the three genes was related to oncogenesis." (PMID 38929750, 2024).
tumor (3 papers, 2021 to 2025). "On the other hand, the organelle hook protein coding gene HOOK2 preferably expressed ENST00000589134 in tumor cells and ENST00000593143 in normal cells and had significantly higher expression levels in tumor cells compared to normal cells." (PMID 37433798, 2023). "For example, we observed that the HOOK2 gene in case 19 was highly expressed in the tumor sample (19T), but not in its matched normal (19N) and stroma (19S) samples, while those genes around HOOK2 (SNORD41, TRIR, and JUNB) had similar levels of expression in all three samples." (PMID 33916417, 2021).
HOOK2 also shares sentences with these, for which no sentence is quoted: ciliopathies (1 paper); Insulin resistance (1); preeclampsia (1).